FOXM1 (forkhead box M1)
Diseases named in the same sentence as FOXM1 in open-access papers (continued):
Sharing a sentence is not in itself a finding about the gene and the disease.
bladder cancer (34 papers, 2017 to 2025). "Previous evidence has established that E2F7 transcriptional factor plays an essential role in the regulation of cell cycle progression; FOXM1 encoded protein is activated in M phase and has been validated as an essential transcriptional factor playing roles in bladder cancer progression." (PMID 35879690, 2022). "Relative research considers that FOXM1 plays an essential role in the phenotype determination and the development of molecular bladder cancer subtypes." (PMID 34885040, 2021). "FOXM1 has been designated as a prognostic marker for bladder cancer and an independent predictor for overall survival and disease-specific survival in muscle-invasive bladder cancer." (PMID 34885040, 2021). "CDKN2A, CTSV and FOXM1 with 95.5% sensitivity and 100% specificity in predicting bladder cancer progression." (PMID 34885040, 2021). "The impact on MIBC and NMIBC as prognostic biomarker superior to clinicopathologic parameters and MKI67, raises FOXM1 to a crucial biomarker for molecular grading and to valuable drug target in bladder cancer." (PMID 29959570, 2018). "FOXM1 is suspected to play a phenotype-determining role in the development of the molecular bladder cancer subtypes and promote its aggressiveness." (PMID 29959570, 2018). "FOXM1 has been shown to be overexpressed on mRNA level as well as on protein level in bladder cancer cells in comparison with normal urothelial cells." (PMID 28498805, 2017). "It has further been shown that elevated FOXM1 transcript levels in bladder cancer correlated with its protein expression." (PMID 28498805, 2017). "The in vitro knockdown of FOXM1 in a bladder cancer cell line showed a decrease of cell migration and proliferation." (PMID 28498805, 2017). "FOXM1 promotes pEMT and the growth of bladder cancer cells partly via HMMR." (PMID 41154660, 2025). "Additionally, it has been reported that abnormal overexpression of FOXM1 leads to upregulation of RNF26 in bladder cancer cells through the MuvB complex." (PMID 38890443, 2024). "The FOXM1/RNF26/p57 axis has been proposed as a new therapeutic target for bladder cancer." (PMID 38890443, 2024). "Previous research successfully identified FoxM1 as an upstream TF of HMMR in bladder cancer." (PMID 36750558, 2023). "Moreover, it has been documented that activated FOXM1 is critical for the progression and drug resistance of bladder cancer." (PMID 34650035, 2021). "Furthermore, we treated bladder cancer cells with a FOXM1-specific inhibitor (FDI-6) to detect changes in RNF26 in T24 cells." (PMID 34650035, 2021). "In addition, we demonstrated that aberrant overexpression of FOXM1 is responsible for the upregulation of RNF26 in bladder cancer cells through the MuvB complex." (PMID 34650035, 2021). "In summary, using a series of bioinformatics and retrospective analyses, the present study identified a subset of seven genes (CDC20, CDKN2A, CTSV, FOXM1, KRT23, MAGEA6, and S100A9), which were significantly associated with progression and prognosis of bladder cancer." (PMID 34885040, 2021). "Additionally, FOXM1 has been shown to be overexpressed on the mRNA and protein levels in bladder cancer cells, and plays an important role in cisplatin resistance, outcome prediction, and risk stratification of patients with BLCA." (PMID 31766561, 2019). "FOXM1 is a highly prognostic marker for bladder cancer disease progression." (PMID 29959570, 2018). "As FOXM1 is a druggable proto-oncogene, the elucidation of its impact on bladder cancer survival may contribute to a further personalization of future NMIBC or MIBC therapy." (PMID 29959570, 2018). "As FOXM1 is a druggable proto-oncogene, the elucidation of its impact on bladder cancer survival may contribute to a further personalization of future MIBC therapy." (PMID 28498805, 2017).
bladder cancer (continued). "As this biomarker improved survival prediction, FOXM1 may be integrated in future biomarker panels for molecular characterization of bladder cancer." (PMID 28498805, 2017). "Therefore, our data suggest that FOXM1 regulates the expression of RNF26 in bladder cancer." (PMID 34650035, 2021). "Thus, the FOXM1/RNF26/p57 signaling axis could be a candidate target for the treatment of bladder cancer." (PMID 34650035, 2021). "Thus, we were curious about whether FOXM1 is responsible for the transcriptional regulation of RNF26 in bladder cancer." (PMID 34650035, 2021). "Furthermore, the study also revealed a three-panel gene set (CDKN2A, CTSV, and FOXM1) that can accurately predict tumor progression and suggested as potential prognostic biomarker(s) for bladder cancer, which could aid in clinical decision making." (PMID 34885040, 2021). "Liu and colleagues reveal that knockdown of GTSE1 reduces the expression of FOXM1 and CCNB1 in bladder cancer, indicating that GTSE1 positively modulates the expression and level of FOXM1." (PMID 38698443, 2024). "Another example is bladder carcinoma (BLCA), which showed a relatively strong correlation (r = 0.48) between FOXM1 and hnRNP C expression." (PMID 37759731, 2023). "Collectively, we uncovered a novel FOXM1/RNF26/p57 axis that modulates the cell cycle process and enhances the progression of bladder cancer." (PMID 34650035, 2021). "The PPI network analysis of three databases identified the following subsets of DEGs, including CDC20, CDKN2A, CTSV, FOXM1, KRT23, MAGEA6, and S100A9, which were significantly upregulated in bladder cancer." (PMID 34885040, 2021). "The expression profile of CDC20, CDKN2A, CTSV, FOXM1, KRT23, MAGEA6, and S100A9 were significantly higher in bladder cancer specimens compared with normal bladder tissue in patients." (PMID 34885040, 2021). "In contrast, ectopic overexpression of FOXM1 enhanced FOXM1 binding to the promoter of RNF26 and increased the RNF26 expression level in bladder cancer cells." (PMID 34650035, 2021). "The FOXM1 signaling network and its regulators, including FOXO3, PI3K, and AKT, remains putative drug targets in bladder cancer which requires additional work." (PMID 34885040, 2021). "The results showed that the formation of FANCD2-foci was significantly reduced by suppression of FOXM1 expression in 5637 and KU7 bladder cancer cell lines." (PMID 32486251, 2020). "Inhibition of FOXM1 expression using siFOXM1 in both 5637 and KU7 bladder cancer cell lines significantly reduced FANCD2 expression at both the mRNA and protein levels." (PMID 32486251, 2020). "Finally, we identified a novel FOXM1/RNF26/p57 signaling axis that modulates the cell cycle process and enhances the progression of bladder cancer." (PMID 34650035, 2021). "A total of seven genes, including CDKN2A, CDC20, CTSV, FOXM1, MAGEA6, KRT23, and S100A9 were confirmed with strong prognostic values in bladder cancer and validated by qRT-PCR conducted in various human bladder cancer cells representing stage-specific disease progression." (PMID 34885040, 2021). "We then assessed whether FOXM1 and FANCD2 affect the recurrence of bladder cancer by analyzing their expression in clinical tissues." (PMID 32486251, 2020). "However, our previous study of gene expression profile analysis identified FOXM1 and FANCD2 as recurrent biomarkers of bladder cancer." (PMID 32486251, 2020). "In addition, expression of FOXM1 as a prognostic factor in the survival of muscle invasive bladder cancer patients, STAT3 expression, and phosphorylation was identified to be substantially higher in basal-like bladder cancer." (PMID 35068946, 2021). "Therefore, we uncovered a novel FOXM1/RNF26/p57 axis in bladder cancer, which could be a candidate target for bladder cancer therapy." (PMID 34650035, 2021). "Thus FOXM1 has global impact on bladder cancer given its role in both muscle invasive and non-muscle invasive tumors." (PMID 29959570, 2018).
bladder cancer (continued). "As luminal and basal bladder cancer subtypes are suspected to present a subtype specific overexpression of other well known drug targets like the FGFR, EGFR and ERBB gene families, the number of promising personalized therapy options rises for FOXM1 enriched MIBC." (PMID 28498805, 2017). "Moreover, we determined the protein levels of FOXM1 and FANCD2 by IHC (Immunohistochemistry) in 57 bladder cancer samples (30 nonrecurrent primary tumors and 27 recurrent primary tumors) using a tissue microarray." (PMID 32486251, 2020).
meningioma (34 papers, 2017 to 2025). A generally slow growing tumor attached to the dura mater. "Previously, NF2 alteration, multiple copy number variations (CNV; e.g. 22q loss, 1p loss, etc.), high FOXM1 expression, low immune cell infiltration, and loss of H3K27me3 were reported as characteristics of aggressive behaviour of meningiomas." (PMID 35570314, 2022). "analyze 160 meningiomas by classifying in 3 groups base on molecular profile and found increased expression of FOXM1 and MYBL2 causing DREAM complex loss of its repressive activity associated with recurrence." (PMID 36033542, 2022). "FOXM1 has also been implicated as one of three genes upregulated in primary atypical meningiomas, which have also been found to demonstrate NF2 loss, genomic instability, mutations in SMARCB1, and a hypermethylated phenotype." (PMID 36686824, 2022). "For example, FOXM1 has been shown to be a critical driver of meningioma aggressiveness and is associated with the activating DREAM complex, thereby allowing cell-cycle progression and cell proliferation." (PMID 33093491, 2020). "For example, the FOXM1 gene, a mitotic transcription factor implicated in a variety of malignant diseases and particularly enriched in invasive meningiomas, is known to be tightly controlled by the epigenetic landscape, with aggressive meningiomas being characterized by DNA hypermethylation." (PMID 38632533, 2024). "Interestingly, the FOXM1 and E2F transcriptional pathways have been found to underlie de novo formation of atypical meningiomas, while progressing meningiomas harbor TERT promotor mutations." (PMID 38730704, 2024). "The colleagues observed that both radiologic and radiomic predictors of adverse meningioma outcomes were significantly associated with molecular markers of aggressive meningioma biology, such as somatic mutation burden, DNA methylation status, and FOXM1 expression." (PMID 35213083, 2022). "First, it is well characterized in the literature that hypermitotic and immune-enriched meningiomas have highly unfavorable clinical outcomes, substantial cell proliferation, and carry nearly total resistance to cytotoxic therapies due to misactivation of FOXM1 and loss of Merlin/NF2." (PMID 40867323, 2025). "Thirdly, the biological roles and specific mechanisms underlying FOXM1 and PRNP in meningiomas warrant in-depth exploration." (PMID 41050085, 2025). "Potential molecular mechanisms of MT include chromosomal abnormalities (Chromosome 22q deletion, NF2 gene mutation, loss of chromosome 1p), genomic alterations (FOXM1, CDKN2A/B and TERTp), and meningioma cancer stem cells." (PMID 39991581, 2025). "Excitingly, accumulating evidences have already established FOXM1 as a critical transcription factor involved in the malignant progression of meningioma." (PMID 41184266, 2025). "FOXM1, one of the earliest transcription factors found to be overexpressed in meningiomas, has emerged as a candidate driver of aggressive phenotypes." (PMID 38730704, 2024). "The last group was hypermitotic meningiomas, with the worst overall survival, characterized by an upregulation of FOXM1 expression." (PMID 39202270, 2024). "MG4 or “proliferative” meningiomas were found to be enriched for cell cycling pathways including MYC, FOXM1, and E2F pathways, had the highest mutational and copy number burden, and were associated with the worst clinical outcomes." (PMID 38695575, 2024). "Over-expression of FOXM1 in vitro were found to lead to increased meningioma cell resistance to cytotoxic chemotherapy." (PMID 36840836, 2023). "An in vivo study utilizing a heterotopic xenograft mouse model demonstrated that FoxM1 is a key transcription factor and oncogenic driver in meningioma progression." (PMID 38001599, 2023). "One recent co-expression module identified, E2F4/FOXM1, predicts increased meningioma aggressiveness, correlating with previous identification of FOXM1 and E2F2 expression networks activated in atypical meningiomas." (PMID 34846640, 2022).
meningioma (continued). "Consistently, when we compared differentially expressed genes between WHO grade I and WHO grade III meningiomas, we found an enrichment of cell cycle, immunoregulator, and FOXM1 target genes in WHO grade III meningiomas." (PMID 32968068, 2020). "Gene ontology analysis revealed that high ADC samples from high grade meningiomas were enriched in Wnt, ectoderm, pluripotency, and neural crest gene expression programs, including FOXM1." (PMID 32968068, 2020). "Nuclear β-catenin and nuclear FOXM1 co-expression were present in 43.33% (13 of 30) of all high-grade meningioma specimens." (PMID 32642722, 2020). "We also provide further evidence that ICG-001 inhibits proliferation of NF2-mutant meningioma cells at least partly through attenuating the FOXM1-mediated Wnt/β-catenin signaling." (PMID 32642722, 2020). "We investigated Merlin and FOXM1 protein expression in a panel of 30 high-grade meningioma samples by IHC staining." (PMID 32642722, 2020). "For example, the FoxM1 target gene in the case of increased FoxM1 mRNA expression was identified by RNA sequencing, DNA methylation sequencing, and target gene expression profile from meningiomas with low survival rate and high local recurrence rate." (PMID 32983987, 2020). "A separate study showed that an increase in FoxM1 expression can be observed in higher-grade meningioma, promoting the expression of β-catenin and cyclin D1, finally leading to proliferation and colony formation in meningioma cells." (PMID 33042832, 2020). "In summary, we have demonstrated for the first time that NF2-associated meningiomas are especially sensitive to ICG-001 in vitro and in vivo partly because of the attenuation of the FOXM1-mediated Wnt/β-catenin signaling." (PMID 32642722, 2020). "A single transcriptome analysis, including the analysis of 280 human meningioma samples, demonstrated that FoxM1 plays a critical role in the proliferation of meningioma, indicating poor clinical prognosis." (PMID 33042832, 2020). "Three clusters where comprised primarily by 2D meningioma cells enriched for metabolic pathways, cell cycle and FOXM1 target genes, and genes involved in extracellular matrix organization and integrin interaction by gene ontology analysis." (PMID 32968068, 2020). "To further characterize downstream signaling pathways modulated in meningioma cells in response to the Merlin/FOXM1/Wnt signaling axis in vitro, we performed western blots for key signaling proteins with CH157-MN and IOMM-Lee." (PMID 32642722, 2020). "Furthermore, it can also be observed in the meningioma organoids that treatment with AZ628 leads to the downregulation of FOXM1 and E2F4." (PMID 41184266, 2025). "The activation of the FOXM1/Wnt signaling axis was observed in aggressive meningiomas." (PMID 41184266, 2025). "FOXM1 was upregulated in premalignant grade 1 meningioma years before the grade 3 transformation." (PMID 39991581, 2025). "In addition, thiostrepton (a FOXM1 inhibitor) in combination with radiotherapy can potently impair the proliferation of malignant meningiomas." (PMID 41050085, 2025). "H3K27ac has a specific activation of genes regulated by FOXM1 in malignant meningiomas." (PMID 41050085, 2025). "However, further research is needed to elucidate the molecular mechanisms underlying the regulation of transcription factors FOXM1 and E2F4 by SLC7A1 in meningioma." (PMID 41184266, 2025). "FOXM1 has been evidenced as a critical transcription factor of benign and malignant meningiomas." (PMID 41050085, 2025). "Gene ontology analysis of RNA sequencing data from Group 2 canine meningiomas, which were enriched for HMRs and cell proliferation pathways (online resource), revealed enrichment of FOXM1, the FOXM1 gene expression program, and cell cycle target genes in comparison to Group 1 and Group 3 tumors." (PMID 38376604, 2024).